ENSG00000251940
Gene: Small nucleolar RNA gene on chromosome 22 (19,249,873 to 19,249,966, forward strand). Ensembl gene ENSG00000251940.
Gene Ontology:
Biological process: RNA processing
Cellular component: nucleolus
Homologues: Orthologues: rat LOC120102010 (73% identical), rat LOC120095412 (72% identical), rat LOC120100361 (72% identical), rat LOC120098361 (71% identical), rat LOC120093419 (70% identical), rat LOC120097583 (69% identical), rat LOC120101238 (67% identical), rat LOC120103272 (67% identical), rat LOC120101239 (62% identical). Paralogues in human: SNORA15 (94% identical), SNORA15B-1 (94% identical), SNORA15B-2 (94% identical).